ZNF517 (zinc finger protein 517)
Description:
May be involved in transcriptional regulation.
Tractability: PROTAC: ubiquitination databases record sites on it.
Gene: Protein-coding gene on chromosome 8 (144,798,866 to 144,811,169, forward strand). Ensembl gene ENSG00000197363.
Subcellular location: Nucleus
Subcellular location (Human Protein Atlas): Nucleoplasm
Pathways (Reactome):
Gene expression (Transcription): Generic Transcription Pathway
Gene Ontology:
Molecular function: DNA-binding transcription factor activity, RNA polymerase II-specific; RNA polymerase II transcription regulatory region sequence-specific DNA binding
Biological process: regulation of transcription by RNA polymerase II; regulation of DNA-templated transcription
Cellular component: nucleoplasm; nucleus
Genetic constraint (gnomAD): Loss-of-function variants: 12 observed, 13.15 expected, observed/expected ratio (o/e) 0.91, 90% interval 0.58 to 1.47. The synonymous counts are far from expectation, so gnomAD's model fits this gene poorly and the ratio says little. Missense variants: 781 observed, 639.18 expected, observed/expected ratio (o/e) 1.22, 90% interval 1.15 to 1.3. Synonymous variants: 388 observed, 287.38 expected, observed/expected ratio (o/e) 1.35, 90% interval 1.24 to 1.47.
Homologues: Orthologues: dog ZNF517 (75% identical). Paralogues in human: ZNF7 (42% identical), ZNF606 (40% identical), ZNF250 (40% identical), ZNF429 (40% identical), ZNF33B (40% identical), ZNF595 (40% identical), ZNF708 (40% identical), ZNF879 (40% identical), ZNF30 (39% identical), MZF1 (39% identical), ZNF311 (39% identical), ZNF471 (39% identical), and 164 more.
Diseases named in the same sentence as ZNF517 in open-access papers:
ZNF517 is named in the same sentence as 3 diseases in open-access papers, as found by Europe PMC text mining. Sharing a sentence is not in itself a finding about the gene and the disease. The quoted sentences say what the papers report.
adrenocortical carcinoma (1 paper, 2019). "In the adrenocortical carcinoma (ACC) cohort, 0.29% of all pooled missense mutations were in the ZNF517 gene (p.V349A), and 0.29% of missense mutations were recurrent GARS (p.P42A) mutations." (PMID 30890735, 2019).
ZNF517 also shares sentences with these, for which no sentence is quoted: autism (1 paper); tumor (1).